SIAH1 (siah E3 ubiquitin protein ligase 1)
Diseases named in the same sentence as SIAH1 in open-access papers (continued):
Sharing a sentence is not in itself a finding about the gene and the disease.
cancer (continued). "In addition, SIAH1 has been demonstrated to regulate multidrug resistance 1 (MDR1)/P-glycoprotein-mediated drug resistance in cancer." (PMID 37062828, 2023). "In addition, SIAH1 has been reported to modulate drug resistance mediated by multidrug resistance 1 (MDR1)/P-glycoprotein in the cancer cells." (PMID 35273154, 2022). "In addition, compared with sensitive EOC patients, SIAH1 was significantly reduced in the serum and cancer tissues of drug-resistant EOC patients." (PMID 35951361, 2022). "The role of the Siah1 E3 ubiquitin ligase in cancer is currently poorly understood." (PMID 25202994, 2014). "Also, inhibition or low levels of Siah1 have been shown to negatively regulate apoptosis, thereby promoting cancer progression." (PMID 25202994, 2014). "Instead, inhibition of SIAH1/2, ubiquitin ligases that regulate AXIN1 stability by associating with its more downstream GSK3 binding domain, might provide an effective strategy to stabilize AXIN1 ΔN cancer variants." (PMID 41550750, 2026). "Thus, SIAH1 has been proposed as a promising therapeutic target in cancer treatment." (PMID 35951361, 2022). "Several E3 ligases trigger mitophagy in cancer cells in a Pink1-dependent but Parkin-independent manner, such as Ariadne RBR E3 Ub protein ligase 1 (ARIH1) and seven in absentia homolog 1 (SIAH-1)." (PMID 36289190, 2022). "We find that SIAH1 and SIAH2 are expressed in all human epithelial cell lines examined thus far, while SIAH3 is only expressed in a limited subset of cancer cell lines." (PMID 28784114, 2017). "This idea is supported by several previous studies that demonstrated that the RING domain-deleted SIAH1 or SIAH2 mutants (termed SIAH1/2 dominant-negative) functionally ablated endogenous activity of SIAH1 and SIAH2 in cancer biology." (PMID 28784114, 2017). "When mRNA expression of SIAH-1 and Kid/KIF22 was analyzed by real-time PCR in normal and cancer breast tissues from the same patient, a large variation in the number of mRNA copies was detected between the different samples." (PMID 20144232, 2010). "Here, we provide further information on the functional role of SIAH1, a significant conditioner of the UPS, in EOC resistance and provide conclusive evidence showing that SIAH1 is down-regulated in drug-resistant EOC cells, patient serum and cancer tissues." (PMID 35951361, 2022). "Hence, SIAH1 would possibly inhibit the invasive action of cancer cells through ERK pathway thus acting as a new therapeutic target in cancer." (PMID 29479529, 2018). "By taking advantage of nonfunctional SIAH3 as a putative endogenous SIAH inhibitor, we may be able to develop a novel anti-SIAH1 and anti-SIAH2 strategy by utilizing SIAH3 expression to antagonize oncogenic K-RAS-driven metastatic human cancer cells." (PMID 28784114, 2017). "To assess the expression of Gp78 in multiple cancers, we used GEPIA-2 analysis to probe TCGA RNAseq data for mRNA expression of Gp78 and other ubiquitin ligases that induce mitophagy (PARK2, RNF185, MUL1, MARCH5, HUWE1, SIAH1) as well as the hypoxia-induced mitophagy proteins BNIP and NIX." (PMID 36284011, 2022).
infection (3 papers, 2017 to 2020). The state of being infected such as from the introduction of a foreign agent such as serum, vaccine, antigenic substance or organism. "As expected, viral titers collected from cells with intact MyD88 were 14- or 44-fold reduced in cells transfected with the SIAH1 siRNA or miR-424 mimic (respectively) prior to infection, as compared to control transfected cells." (PMID 32117091, 2020). "SIAH1 mRNA was detectable at 24 h p.i. and increased to more than 20-fold above constitutive levels by 48 h post-infection." (PMID 32117091, 2020). "Because we observed that degradation of MyD88 during infection occurs in a proteasome-dependent manner, we next examined the physical interaction between MyD88 and SIAH1." (PMID 32117091, 2020). "Inhibition of SIAH1 during infection results in increased innate immune signaling, but this increase, as well as inhibition of viral replication, is abrogated in cells in which the MyD88 gene has been deleted." (PMID 32117091, 2020). "We therefore sought to determine if the antiviral effects of SIAH1 knockdown and miR-424 expression are a result of increased MyD88-dependent intracellular immune signaling during infection." (PMID 32117091, 2020). "Here, we show that abolishing the ICP0:SIAH-1 interaction affects the HSV-2 phenotype during infection." (PMID 30080903, 2018). "Although ETS2 and Siah1 expressed from 1 h p.i., 3 and 6 h infection resulted in highly-induced expression of both of these proteins." (PMID 28481365, 2017). "However, in cells that were transfected with the SIAH1 siRNA or miR-424 mimic prior to infection, MyD88 expression was restored, suggesting that SIAH1 plays a role in the repression of MyD88 in DENV2 infected cells (lanes 3–4)." (PMID 32117091, 2020). "Result showed that although Siah1 interacted with β-catenin in uninfected or infected cells at 14 h and in uninfected cells at 20 h, β-catenin was completely lost in the immunoprecipitate only after 20 h of infection." (PMID 28481365, 2017). "Infection was also inhibited by SMURF2 knockdown, although to a lesser extent than the SIAH1 knockdown or miR-424 expression." (PMID 32117091, 2020). "Western blot analysis revealed that although MOI 100 at 6 h post infection (p.i.)and MOI 200 at both 3 h and 6 h significantly induced Siah1 protein, MOI 200 at 6 h was maximally effective." (PMID 28481365, 2017). "Like SIAH1, miR-424 inhibited expression of SMURF1 and SMURF2 during DENV2 infection." (PMID 32117091, 2020). "Titer measurements revealed that comparable amounts of viral wild-type and NxN1/2 mutant particles were detected in the TG at day 3 post infection, suggesting that the ICP0:SIAH-1 interaction is not required for virus dissemination from the eye to the innervating neurons." (PMID 30080903, 2018).
neurodegenerative disease (1 paper, 2017). A disorder of the central nervous system characterized by gradual and progressive loss of neural tissue and neurologic function. "In addition, GAPDH has been suggested to have high affinity for AD-associated proteins, including β-amyloid, β-amyloid precursor protein, and tau, and to be involved in the NO/GAPDH/Siah-1 apoptotic cell death cascade, particularly in neuronal cell death associated with neurodegenerative diseases." (PMID 28251161, 2017).
neurodevelopmental disorder (1 paper, 2025). A behavioral and cognitive disorder with onset during the developmental period that involves impaired or aberrant development of intellectual, motor, or social functions. "We advocate for the inclusion of SIAH1 in diagnostic panels for patients with unexplained neurodevelopmental disorders and multisystem dysmorphisms." (PMID 41574050, 2025).
SIAH1 also shares sentences with these, for which no sentence is quoted: bladder cancer (3 papers); Cerebral ischemia (2); esophageal cancer (2); abortion (1); adenocarcinoma (1); Alzheimer disease (1); colon adenoma (1); congenital muscular dystrophy (1); Dengue Virus Infection (1); diabetic nephropathy (1); Hyperglycemia (1); ischemia (1); kidney disease (1); metastatic cancer (1); ovarian cancer (1); pancreatic cancer (1); premature ovarian failure (1); prostate carcinoma (1); spinal cord injury (1); sterility (1).